TFF2 (trefoil factor 2)
Diseases named in the same sentence as TFF2 in open-access papers (continued):
Sharing a sentence is not in itself a finding about the gene and the disease.
colorectal tumors (2 papers, 2015 to 2019). "TFF2 is attractive candidate for clinical use in cancer therapy, given its ability to suppress MDSCs and enhance CD8+ T cell infiltration of colorectal tumors." (PMID 30042499, 2019). "The up-regulated of PAR4 and TFF2 in colorectal tumors were 58% (22 of 38) when compared with the matched non-neoplastic mucosa." (PMID 25876034, 2015).
Crohn disease (2 papers, 2013 to 2024). A gastrointestinal disorder characterized by chronic inflammation involving all layers of the intestinal wall, noncaseating granulomas affecting the intestinal wall and regional lymph nodes, and transmural fibrosis. "A scRNA-seq study of paediatric treatment-naive patients with Crohn’s disease identified MUC6+TFF2+ and BPIFB1+AQP5+ populations, albeit annotated as goblet cells." (PMID 39567783, 2024). "No staining for TFF2 was seen in goblet cells in normal colon tissue whereas the majority of tissue sections in ulcerative colitis and Crohn’s disease showed sparse and scattered TFF2 positive goblet cells." (PMID 23691218, 2013).
cystic fibrosis (2 papers, 2020 to 2022). Autosomal recessive disorder caused by pathogenic variants in the CFTR gene (cystic fibrosis transmembrane conductance regulator), which encodes a chloride and bicarbonate channel expressed in epithelial cells, and follow the diagnosis criteria. "Furthermore, in cystic fibrosis airways, TFF3 synthesis increased in surface goblet cells, whereas the elevated expression of TFF1 and TFF2 occurred in mucous cells of submucosal glands." (PMID 36499686, 2022).
lung carcinoma (2 papers, 2012 to 2015). "It was found that TFF1 and TFF2 have similar or slightly higher levels in these three subtypes of lung cancer compared to healthy individuals, while TFF3 levels were significantly higher in the examined lung cancer cases compared to healthy individuals." (PMID 22246423, 2012). "However, the levels (the mean OD values of the respective bands) of TFF1 and TFF2 in lung cancer patient were similar to those in healthy individuals." (PMID 22246423, 2012). "It was found that TFF1 and TFF2 levels were similar or slightly higher in these three subtypes of lung cancer compared to those in healthy individuals, while TFF3 levels were significantly higher in the detected lung cancer cases compared to healthy individuals." (PMID 22246423, 2012). "Immunoblot analyses of TFF1, TFF2 and TFF3 indicated that lung cancer tissues and lung cancer cell lines have higher expression levels of TFF3 protein, but not of TFF1 and TFF2 proteins, compared to tissues from healthy individuals or from normal cell line." (PMID 22246423, 2012). "In this study, we investigated the protein and mRNA levels of TFF1, TFF2 and TFF3 in tissues of lung cancer patients and healthy individuals, and lung cancer cell lines and normal cell lines." (PMID 22246423, 2012). "In our experiments, it was found that TFF1 and TFF2 levels (for the mean values of all detected patients) in the serum of lung cancer patients were slightly higher than in healthy individuals." (PMID 22246423, 2012). "Levels of TFF1 and TFF2 transcripts in lung cancer cell lines (LK-2, A549 and MS-1) were slightly higher or not significantly different from those in the normal cell line NuLi-1." (PMID 22246423, 2012). "Levels of TFF1 and TFF2 in lung cancer tissues were slightly higher or not significantly different from those in normal tissues from the 60 healthy individuals." (PMID 22246423, 2012). "Quantitative RT-PCR analysis indicated higher levels of TFF3, but not TFF1 and TFF2, transcripts in lung cancer tissues or cell lines." (PMID 22246423, 2012). "However, the roles of TFF1, TFF2 and TFF3 are still unclear in the prediction and prognosis of lung cancer." (PMID 22246423, 2012). "Levels of TFF1 and TFF2 in lung cancer cell lines (LK-2, A549 and MS-1) were slightly higher or not significantly different from those in the normal cell line NuLi-1." (PMID 22246423, 2012). "Levels of TFF1 and TFF2 transcripts in lung cancer tissues were slightly higher or not significantly different from those in normal tissues from the 60 healthy individuals." (PMID 22246423, 2012). "Quantitative RT-PCR analysis of TFF1, TFF2 and TFF3 transcripts in tissues and cell lines indicated higher levels of TFF3, but not of TFF1 and TFF2 transcripts in lung cancer tissues or cell lines when compared with those in tissues of healthy individuals and normal cells." (PMID 22246423, 2012). "Immunoblot analyses of TFF1, TFF2 and TFF3 indicated that lung cancer tissues and lung cancer cell lines have a higher expression of the TFF3 protein, but not of TFF1 or TFF2 proteins, compared to tissues from healthy individuals or from the normal cell line." (PMID 22246423, 2012).
oral squamous cell carcinoma (2 papers, 2017 to 2021). "In salivary gland tumors, a higher expression of TFF1, TFF2, and TFF3 was found, while in oral squamous cell carcinoma TFF2 and TFF3, but not TFF1, were downregulated with respect to healthy tissue." (PMID 29296124, 2017).
pancreatic ductal adenocarcinoma (2 papers, 2018 to 2020). An infiltrating adenocarcinoma that arises from the epithelial cells of the pancreas. "Another study revealed that TFF2 reduced proliferation of pancreatic ductal adenocarcinoma." (PMID 32122390, 2020).
ulcer (2 papers, 2010 to 2014). "In tissue at Day 7 and Day 30 after H. pylori inoculation (or 9 and 32 days post-ulcer induction), we observed the gastric epithelium still displayed altered distributions of H,K-ATPase and TFF2." (PMID 25033386, 2014). "Parietal cells, which had vanished in the active ulcer, reappeared above and below the TFF2 cell population in the mucosa of the healing ulcer." (PMID 20565818, 2010). "During ulcer healing, the TFF2 cell population expanded from the base to the neck of glands." (PMID 20565818, 2010).
autoimmune gastritis (1 paper, 2021). Inflammation of the body fundic mucosa of the stomach. "We reviewed consecutive 22 Japanese patients with autoimmune gastritis (AIG) to investigate TFF2 expression in pyloric and pseudopyloric metaplasias by counting all pyloric gland-like glands in biopsy specimens taken from greater curvature of the middle corpus according to the Updated Sydney System." (PMID 33515301, 2021).
bile duct cancer (1 paper, 2014). "Breast, pancreas and bile duct cancer cell line experiments suggested that TFF2 expression induces cell migration via Platelet-Activation Receptor 4 (PAR4) and Panc1 activation, as well as mitosis via EGFR/MAPK axis signaling." (PMID 24555920, 2014).
C. perfringens infection (1 paper, 2020). "In the present study, the expression of occludin, ZO-1, GLP2, OGG1 and TFF2 genes increased in the wall of the small intestine, which indicates that C. perfringens infection in turkeys compromised intestinal barrier integrity." (PMID 32264939, 2020). "The expression of occludin, ZO-1, GLP2, OGG1 and TFF2 genes increased in the wall of the ileum (P < 0.001) in response to C. perfringens infection." (PMID 32264939, 2020). "Clostridium perfringens infection increased the expression of occludin, ZO-1, GLP2, OGG1 and TFF2 genes (P < 0.001) in the wall of the ileum." (PMID 32264939, 2020).
cyst (1 paper, 2019). A sac-like closed membranous structure that may be empty or contain fluid or amorphous material. "Before the development of the cystic glands, the epithelium of the gastric mucosa showed aggravated cyst formation and TFF2-positive SPEM-like lesions, and the cell proliferation zone shifted from the isthmus to the base of the glands." (PMID 31226941, 2019). "TFF2+ reactions were mainly observed at the apical portion of large EM cyst lining cells and some epithelial cells were positive for both pepsinogen and TFF2." (PMID 31226941, 2019).
diabetic nephropathy (1 paper, 2017). "TFF2 serum levels were significantly higher in patients with vascular nephropathy or diabetic nephropathy as compared to patients suffering from glomerulonephritis." (PMID 28355260, 2017). "Besides varying TFF2 levels in different CKD stages, we found significantly increased TFF2 serum levels in patients with vascular or diabetic nephropathy as compared to patients with glomerulonephritis." (PMID 28355260, 2017). "Furthermore, patients suffering from vascular or diabetic nephropathy had significantly higher TFF2 serum levels as compared to patients with glomerulonephritis." (PMID 28355260, 2017).
end-stage renal disease (1 paper, 2017). "Therefore, the inclusion of additional patients with different renal diseases and CKD stages would increase statistical power and might help to unravel the role of TFF2 in the acute phase of renal failure and during progression to end-stage renal disease." (PMID 28355260, 2017).
endocervical adenocarcinoma (1 paper, 2021). An adenocarcinoma that arises from the endocervix. "Gastric-type endocervical adenocarcinomas are positive for Trefoil Factor 2 (TFF2), CK7, CEA, and CAIX and up to 50% can be positive for CK20 and CDX2 28,47." (PMID 33570865, 2021).
eosinophilia (1 paper, 2019). "Accordingly, there was increased expression of Muc5ac, pro-Th2 and Th17 cytokine (e.g., Il13, Il33 and Il17a), increased BALF eosinophilia, as well as increased genes involved in epithelial repair responses in the lungs (e.g. Egfr and Tff2)." (PMID 31089182, 2019).
gastric adenoma (1 paper, 2014). A neoplastic polyp that arises from the stomach. "However, several studies have shown that TFF2 expression is decreased significantly in gastric adenomas compared with the associated normal tissue, suggesting that the loss of TFF2 expression, as with the loss of TFF1, is an important event in gastric carcinogenesis." (PMID 24765170, 2014).
glomerulonephritis (1 paper, 2017). A renal disorder characterized by damage in the glomeruli. "Fractional TFF2 excretion was significantly elevated in patients with glomerulonephritis as compared to patients with vascular nephropathy." (PMID 28355260, 2017).
hookworm infection (1 paper, 2021). "Overall, TFF2 elevation is specifically associated with Hookworm infection, especially in females, while TFF3 elevation is associated with Schistosoma infection and females have higher levels in general in a mostly adult population." (PMID 34662329, 2021). "Because Hookworm infection was associated with higher levels of TFF2, but individuals may have varying degrees of parasite burden, we collected a second larger dataset and used a regression between serum TFF2 and fecal egg counts with the covariate of age." (PMID 34662329, 2021). "In the mouse hookworm infection model N. brasiliensis, TFF2 is required for induction of IL-33, early Type 2 cytokine responses, and contributes to clearance of worms from the gut." (PMID 34662329, 2021). "In contrast to hookworm infection, S. hematobium infection in children was associated with a decrease in both TFF2 and TFF3 in the serum, but not the urine." (PMID 34662329, 2021). "Exogenous TFF2 was associated with suppressed TNF-α and IFN-γ production by stimulated human PMBCs, suggesting that elevated TFF2 in the context of hookworm infection could reduce these pro-inflammatory cytokine levels through direct or indirect mechanisms in vivo." (PMID 34662329, 2021). "We have previously shown critical roles for TFF2, TFF3 and the alarmin cytokine IL-33 in protective immune responses in a murine model of hookworm infection, which needs to be confirmed in human infection." (PMID 34662329, 2021). "TFF2 was specifically elevated by hookworm infection in women and increased with age rather than parasite burden." (PMID 34662329, 2021). "This response was significantly repressed by co-treatment with rh-TFF2, but not rh-TFF3, indicating that elevated TFF2 could contribute to suppressed inflammatory responses in the context of hookworm infection." (PMID 34662329, 2021).
immune deficiency (1 paper, 2012). "TFF2 is found more abundantly during repair in areas of proliferation, while Tff2-deficient mice exhibit immune deficiency, increased acid secretion and increased susceptibility to NSAID injury." (PMID 22245972, 2012).
intraductal papillary mucinous neoplasms (1 paper, 2023). "Loss of pancreatic Tff2 has been shown to promote formation of intraductal papillary mucinous neoplasms in mice." (PMID 37628863, 2023).
liver diseases (1 paper, 2021). "TFF2 is also increased in mice with liver injury, which indicates a potential role in the pathogenesis of liver diseases." (PMID 34146542, 2021). "Because liver fibrosis is highly correlated to the development of HCC, we ask whether TFF2 is involved in the progression of liver diseases." (PMID 34146542, 2021).
liver fibrosis (1 paper, 2021). "Future research will be needed to determine whether TFF2 could be detected in the circulation and whether neutralizing TFF2 would ameliorate liver fibrosis in different models of liver injury." (PMID 34146542, 2021).
metastatic cancer (1 paper, 2021). A carcinoma which has spread from the original site of growth to another anatomic site. "However, although Cluster 0 contained comparable cell number from primary and metastatic cancer, some of its signatures were similar to those of primary PDAC cancer cells, LINC01133 and trefoil family member gene TFF2, for example." (PMID 34055623, 2021).
metastatic tumors (1 paper, 2021). "DIRAS1, FBXL16, TP53I11, TFF2, and ZNF467 were upregulated in both metastatic tumors and GHSROS-overexpressing PC3 and LNCaP cells, while AASS, CHRDL1, CNTN1, IFI16, and MUM1L1 were downregulated." (PMID 33585078, 2021).
mucinous neoplasm (1 paper, 2023). "This view is supported by a report that a loss of Tff2 promotes the formation of pancreatic intraductal mucinous neoplasms." (PMID 37108221, 2023).
nasopharyngitis (1 paper, 2022). An inflammatory process that affects the nasopharynx. "Nasopharyngitis (16.7% in the TFF2-IFN group and 0% in the placebo group), which was local effects, not systemically derived." (PMID 36578554, 2022).
nephropathies (1 paper, 2017). "TFF2 serum and urine concentrations as well as fract TFF2 excretion analysed within nephropathies diagnosed in more than 10 patients." (PMID 28355260, 2017).
osteoarthritis (1 paper, 2019). A noninflammatory degenerative joint disease occurring chiefly in older persons, characterized by degeneration of the articular cartilage, hypertrophy of bone at the margins and changes in the synovial membrane. "Gene expression of TFF1, TFF2, and TFF3 of healthy, osteoarthritis (OA), and rheumatoid arthritis (RA) affected SM was analyzed by semi-quantitative PCR." (PMID 31817054, 2019).
pancreatitis (1 paper, 2023). Inflammation of the pancreas. "For example, TFF2 is upregulated in a murine pancreatitis model and in human pancreatitis, as well as in pancreatic carcinoma." (PMID 37108221, 2023).
periampullary adenocarcinoma (1 paper, 2025). An adenocarcinoma that arises from the periampullary region. "The corresponding ROC curves were performed to further illustrate the diagnostic efficacy of serum TFF2, yielding an AUC of 0.947 for differentiating PC from normal individuals and 0.856 for distinguishing PC from periampullary adenocarcinoma." (PMID 41040532, 2025). "Additionally, the GSE15471, GSE16515, GSE32676, and GSE39409 datasets were integrated to further investigate the diagnostic potential of TFF2 in differentiating PC from periampullary adenocarcinoma." (PMID 41040532, 2025). "We measured TFF2 levels in serum samples from healthy controls, as well as patients with PC and periampullary adenocarcinoma and found that TFF2 was specifically overexpressed in PC patients, but not in periampullary adenocarcinoma patients or healthy controls." (PMID 41040532, 2025). "However, serum TFF2 concentrations were elevated in PC patients compared to both normal individuals and periampullary adenocarcinoma patients (P<0.001)." (PMID 41040532, 2025). "Importantly, serum TFF2 levels were significantly elevated in the PC group, with AUC values of 0.947 for distinguishing PC from normal controls and 0.856 for differentiating it from periampullary adenocarcinoma, outperforming CA199 and CEA." (PMID 41040532, 2025). "The combination of TFF2 enhanced accuracy of CA199 and CEA to discriminate PC from periampullary adenocarcinoma." (PMID 41040532, 2025). "Also, TFF2 expression levels in PC were notably higher than those observed in benign pancreatic conditions, CCA, HCC, and periampullary adenocarcinoma, with statistically significant differences." (PMID 41040532, 2025).
periodontitis (1 paper, 2023). An acute or chronic inflammatory process that affects the tissues that surround and support the teeth. "It highlights changes in the ratio and functionality of immune and epithelial cells, and uncovers a distinctive epithelial subcluster and elevated Tff2 expression related to APDC deficiency during periodontitis." (PMID 37928259, 2023). "Furthermore, the presence of the distinctive epithelial subpopulation and significantly elevated Tff2 levels in the lncR-APDC-silenced EP model offer new perspectives on the epigenetic regulation of periodontitis pathogenesis." (PMID 37928259, 2023). "Additionally, the identification of unique epithelial cell subsets and the interaction between lncR-APDC and Tff2 open new avenues for understanding the epigenetic regulation of periodontitis." (PMID 37928259, 2023). "Furthermore, we observed that TFF2 protein exhibited high expression levels specifically within the APDC-KO periodontitis samples." (PMID 37928259, 2023).
prostate tumors (1 paper, 2016). "As examples, the expression of Tff2 and Ptn in individual prostate tumors, as determined by q-PCR analysis, is shown." (PMID 26807730, 2016).
severe combined immunodeficiency (1 paper, 2016). Severe combined immunodeficiency (SCID) comprises a group of rare monogenic primary immunodeficiency disorders characterized by a lack of functional peripheral T lymphocytes resulting in early-onset severe respiratory infections and failure to thrive. "After one dose of Ad-Tff2 (5 × 108 pfu/mouse), TFF2 was detected in peripheral blood of Tff2-null, wild-type and nonobese diabetic/severe combined immunodeficiency (NOD–SCID) mice." (PMID 26841680, 2016).
squamous cell lung carcinoma (1 paper, 2012). A carcinoma arising from squamous bronchial epithelial cells. "TFF2 levels were also slightly higher than those in healthy individuals (squamous cell lung carcinoma, 234.2±58.9; adenocarcinoma, 245.8±37.6; SCLC, 239.4±68.5; healthy individuals, 131.7±44.1)." (PMID 22246423, 2012).